DCAF13P3 (DDB1 and CUL4 associated factor 13 pseudogene 3)
Gene: Processed pseudogene on chromosome 15 (50,944,663 to 50,945,996, forward strand). Ensembl gene ENSG00000259378.
Diseases named in the same sentence as DCAF13P3 in open-access papers:
DCAF13P3 is named in the same sentence as 1 disease in open-access papers, as found by Europe PMC text mining. Sharing a sentence is not in itself a finding about the gene and the disease. The quoted sentences say what the papers report.
tumor (1 paper, 2020). "Only a single up-regulated gene, DCAF13 (DDB1 and CUL4 associated factor 13) (boxed in orange) was found to be correlated with the only up-regulated tumor capsule specific lncRNA, DCAF13P3 (boxed in orange)." (PMID 32636408, 2020).